TNF (tumor necrosis factor)
Diseases named in the same sentence as TNF in open-access papers (continued):
Sharing a sentence is not in itself a finding about the gene and the disease.
infection (continued). "The downregulation of TNF-α and IL-1β genes may indicate aggressive virulent behavior of P. aeruginosa and F. oxysporum, which might have suppressed or delayed a ubiquitous immune response to a robustly developing infection." (PMID 37569767, 2023). "Proinflammatory cytokines, which are produced at the site of infection by activated accessory immune cells, leading to endocrine, autonomic and behavior changes, include interleukin-1α and β (IL-1α and IL-1β), tumor necrosis factor-α (TNF-α) and interleukin-6 (IL-6)." (PMID 37582716, 2023). "Moreover, the pDC-dependent increase in IL-6 and TNF levels was observed only when pDCs were in direct contact with MDMs, further supporting an additive/promotive role of pDCs in this cellular response to infection." (PMID 37253946, 2023). "Furthermore, it moderately increased the expressions of proinflammatory cytokines including IL-1β, IL-6, and TNF-α in the early stage of infection and decreased their release rapidly in the later stage, while regulated the same phase change of anti-inflammatory cytokine IL-10." (PMID 35071595, 2022). "However, neither multivariable analysis of anti‐TNF use in 3000 CD patients nor meta‐analysis of over 5000 patients from controlled trials has revealed any increased risk of mortality from infection versus other IBD treatments or placebo, respectively." (PMID 35301734, 2022). "Since 20% of participants in both cohorts report resolution of PASC between 4 and 12 weeks after infection, we asked whether there are trends toward normalization of IL-1β, IL-6, and TNF levels with elapsed time after infection in individuals reporting ongoing symptoms." (PMID 35732153, 2022). "Also, while low levels of TNF-α were detected in in vitro differentiated human osteoblasts and in the MG-63 cell line in basal conditions, a marked increase was observed in MG-63 upon infection." (PMID 36483565, 2022). "Because we observed significant changes in the levels of HMW adiponectin in the hearts during infection, which may affect immune signaling, we analyzed the levels of infiltrated macrophages and the levels of proinflammatory TNFα in the hearts by immunoblot analysis." (PMID 35369283, 2022). "The authors hypothesized that TNF-α and IFN-α may disrupt tight junctions of the endocervical columnar epithelial barrier, which would make it easier for HIV to access underlying target cells, and dually increase the likelihood of infection." (PMID 36303679, 2022). "Since the inducible expression of TNF-α, IFN-γ, and Granzyme B are highly associated to T-cell cytotoxicity, our results implied that TGF-β1 might inhibit the effector function of tilapia T cells to eliminate pathogenic infection." (PMID 36581209, 2022). "Like the wild type, infection with the mutant cultured in either the LSMMG or control condition elicited robust upregulation of genes associated with inflammation, response to LPS, cell chemotaxis, NF-κB and TNF signaling relative to the time-matched uninfected culture." (PMID 35711662, 2022). "Also, MC-derived TNFα may play a role in the early steps of infection since it is stored in granules and can be immediately released after infection." (PMID 35720353, 2022). "The TNF-α upregulates adhesion molecules on the blood vessel endothelial cell surface to increase influx of inflammatory cells, including the monocytes themselves but primarily neutrophils, and the chemokines guide the inflammatory cells into the area of infection and enhance phagocytic activity." (PMID 35409250, 2022). "There was, however, an increased risk of infection in mothers exposed to anti-TNF, similar to that in non-pregnant women; risk of infection did not increase when medication was continued beyond 24 weeks, but discontinuation before Week 24 increased risk of flare." (PMID 36225722, 2022).
infection (continued). "This means that a large subpopulation of CD patients may not benefit from the long-term use of TNF-α monoclonal antibodies because it impedes the host’s ability to effectively mitigate infection, which is, ironically, the causative agent for disease." (PMID 35585977, 2022). "These contrasting findings emphasize the potential duality of some cytokines such as IFNs and TNF that are essential to confer immunity against infection but may have the potential to augment disease progression, often due to a dysregulation of timing and location." (PMID 36129445, 2022). "Among the hypotheses, it is thought that, as for the olfactory mucosa, the expression of ACE-2 receptors in the oral mucosa, ascertained in the taste buds, can favor the infection and therefore induce a “cytokine storm” due to TNF-α, IL-6, and IFN-γ overexpression." (PMID 35269410, 2022). "The present study, revealed the significant up-regulation of pro-inflammatory cytokines, such as, IL-1β, IL-6, IL-10, IFN-γ and non-significant elevation of TNF in infected controls on the 9th day post-infection, showing an association with disease severity that supports previous findings." (PMID 36510199, 2022). "Notably, KEGG enrichment analysis of the DEGs during infection showed an enrichment of multiple immune-related signaling pathways of the host, including the tumor necrosis factor (TNF) signaling pathway and mitogen-activated protein kinase (MAPK) signaling pathway." (PMID 36352407, 2022). "Although TNFR1/2 deficiency throughout infection or TNF-α blockage at early disease stages led to impaired immune responses and severe disease outcomes, it was unclear whether TNF is essential for pathogen control or for disease pathogenesis at late stages of infection." (PMID 35479068, 2022). "Despite not controlling the increase in IL-6 and IFN-γ, inhibition of HO-1 significantly reduced TNF levels when compared with pregnant infected mice treated with vehicle (p=0.0392), suggesting that ZnPPIX is able to control, at least in part, infection-induced inflammation at implantation sites." (PMID 35619717, 2022). "Nevertheless, combination therapy increases the risk of tumors and infections, so in patients with risk factors for infections and/or tumors and for the development of immunogenicity, non-anti-TNF biologics may be a better option." (PMID 35160280, 2022). "Therefore, a channelling bias might be at least partially responsible for this observation, as patients with recurrent infections on previous therapies may rather be started on anti-IL17 than anti-TNF medication in clinical practice." (PMID 36389682, 2022). "Circulating neutrophils are drawn toward sites of inflammation or infection by locally released chemotactic agents such as constituents of a pathogen and chemoattractants secreted from damaged tissues or infiltrating leukocytes, including tumor necrosis factor (TNF)-α, interleukin (IL)-1, and IL-8." (PMID 35456003, 2022). "Moreover, a rodent model of infection with Giardia showed increased levels of TNFα in plasma." (PMID 36232855, 2022). "However, MIA has been associated with an increase in cytokine synthesis and release, including IL-6 and IFN-γ among others (e.g., IL-1β, TNF-α) in response to infection and external factors during pregnancy both clinically and in experimental in vivo models of MIA." (PMID 36300375, 2022). "In the study in focus, an increase cardiac IFN-γ was observed in both groups infected when compared with respective controls, although only in IL-32γTg mice T. cruzi infection induced significant high levels of TNF-α, which may be related to the better control of infection observed in these animals." (PMID 35097133, 2022).
infection (continued). "HIV-infected children have also been noted to accumulate bone density more slowly than non-infected children through direct infection of bone cells causing elevation of several cytokines (interleukin 1, interleukin 6, and tumor necrosis factor-α) that contribute to increased activity of osteoclasts." (PMID 36199047, 2022). "Since we have shown a significant association between IL-6 and TNF-α and functional outcomes in a group of patients without prior infection and other chronic inflammatory diseases, we can conclude that IL-6 and TNF-α are inflammatory markers of acutely ischemic brain injury." (PMID 36142524, 2022). "It is important to note that while TNF inhibitor use may aid in recovery from P. jirovecii infections, it does not mean that individuals taking TNF inhibitors are not predisposed to secondary infections or even reinfection." (PMID 36159650, 2022). "However, we can observe that these gene expressions responded dose-dependently to secondary treatment of TNFα (5 and 10 ng/ml) (P < 0.05), suggesting that the increase of TNFα during infection may synergistically aggravate production of other cytokines." (PMID 35941890, 2022). "Stressed mice show higher levels of tumor necrosis factor (TNF) and suppression of the anti-inflammatory cytokine IL-10 before the pathogen challenge, suggesting an immunomodulatory effect of dysbiosis microbiota, which renders the host more susceptible to infection." (PMID 35185849, 2022). "Similarly, E. coli 1587 infection dramatically stimulated the upregulation of IL-1β, IL-6, IL-10, and TNF-α mRNA transcription levels in mice colons 3 days post infection, but this phenomenon mostly diminished by 7 days post infection except for IL-6." (PMID 35399688, 2022). "The resistance characteristic to infection with the ME49 strain of T. gondii exhibited by BALB/c mice can be exemplified by the significantly lower number of cysts observed when compared to C57BL/6 mice, associated with lower levels of TNF-α and IL-12, and higher levels of TGF-β." (PMID 36566237, 2022). "Each of these characteristics may be available at bedside in parallel of the assessment of infection, organ dysfunction, pro- (for example TNFα and/or IL-18) and anti-inflammatory (for example IL-1Ra and/or IL-10) cytokines, and markers of adaptive function (for example HLA-DR)." (PMID 36301921, 2022). "The study further examined different key immune genes such as the transcript level of tumor necrosis factor-alpha (TNFα), interleukin-6 (IL-6), interleukin-8 (IL-8), interleukin-10 (IL-10), interleukin-1 beta (IL-1β), and transforming growth factor-beta 1 (TGFβ1) during the early phase of infection." (PMID 36145441, 2022). "However, Interferon gamma (IFNγ) and tumor necrosis factor (TNF) could be detected in respective tests for this subject 6 weeks after infection." (PMID 35577791, 2022). "Therefore, we tested whether the improved culture conditions also had an impact on the TNF-α secretion after infection by B. taylorii at early time points." (PMID 35910598, 2022). "When an organism is under injury, infection, and inflammation, the activated monocytes and injury tissue can secret pro-inflammatory cytokines, such as interleukin-1 (IL-1), interleukin-6 (IL-6), and tumor necrosis factor (TNF-α), which can induce the secretion of APPs." (PMID 34941838, 2021). "Moreover, the expression of the cytokines IL-1β, IFN-γ, IL-6, TNF-α, and TGF-β was higher in HDV-∆L-HDAg mice than in HDV-WT at days 14 and 21 post-infection, in agreement with the increased liver damage observed at these time points; however, only the expression of TNF-α was significantly higher." (PMID 33925087, 2021). "Induction of mICAM-1 expression in AEC has been observed with infection by H. influenzae, C. pneumoniae, Pneumocystis carinii or P. aeruginosa as seen in our study, either directly in response to bacterial products, or indirectly in response to inflammatory cytokines such as TNF-α." (PMID 33690714, 2021).
infection (continued). "Additionally, S. mansoni-infected SCID mice displayed normal levels of TNF expression, suggesting that other cells may be the major source of TNF during the infection." (PMID 33465071, 2021). "Since this pathway was shown to regulate the concentration of effector molecules and antibodies during the infection, future projects could evaluate the use of TNF as an immune modulator, aiming to reduce tissue inflammation and cerebral parasite burden in models of clinical neosporosis." (PMID 35071042, 2021). "There is growing evidence that CRP plays important roles in inflammatory processes and host responses to infection including the complement pathway, apoptosis, phagocytosis, nitric oxide (NO) release, and the production of cytokines, particularly interleukin-6 and tumor necrosis factor-α." (PMID 33534859, 2021). "Interestingly, infected Lgals3–/– mice showed a drop in serum levels of Th1 and Th2 cytokines, including IFN-γ, IL-2, IL-5, IL-6, IL-10, and TNF, compared with WT mice; these differences were significantly pronounced at 14 days but ceased at 28 days post-infection." (PMID 35046919, 2021). "Given the key role of TNF in promoting hepatocytic apoptosis, TNF antagonists are effective therapies in blocking viral replication but in patients with active infection and in the presence of detectable serum HBV surface antigen (Hbsag) this treatment may cause reactivation of the HBV virus." (PMID 34503196, 2021). "Firstly, as the previous studies have reported, low pathogenic PRRSV-like CHsx1401 enhanced the production of pro-inflammatory cytokines including IL-1, IL-6 and TNF-α in PAMs and serum, which could inhibit infection of other pathogens through the activation of NF-КB pathway or STAT pathway." (PMID 33797313, 2021). "However, these adhesion molecules and chemokine expression which are upregulated at the later phase of infection by TNF from infected monocytes may recruit mononuclear leukocytes and amplify more inflammation during OT infection." (PMID 34368012, 2021). "Besides, TNF-α and IL-6 are pleiotropic cytokines produced mainly by neutrophils, which participate in cell trafficking, inflammatory responses, and host defense against infection." (PMID 33815381, 2021). "However, manipulation of these defenses and damage by the infection may lead to aberrant responses characterized by the unchecked release of pro-inflammatory cytokines such as IL-1α, IL-1β, TNFα, IFN-γ, and IL-6." (PMID 34440903, 2021). "Thus, TNFα production seems to be related to a parasitaemia control mechanism, since animal E2, in which an excellent response to T. vivax was observed, presented high expression of this cytokine during the sub-patent phase of the infection." (PMID 34827923, 2021). "Given that TFF2 is low in younger populations and further reduced in S. haematobium infected children, this could possibly explain why TNFα is high in urine and by proxy the infection site of the bladder and urinary tract, where S. haematobium eggs emerge from tissue into the urine." (PMID 34662329, 2021). "Distinct from the other groups, infection in LP 3%-fed mice did not increase the levels of TNF, which may be associated with the changes observed in liver pathology in this experimental group." (PMID 33815321, 2021). "As described in the previous section, infection of the epithelial-endothelial barrier and of alveolar macrophages releases a flood of chemoattractant molecules as well as a variety of activating and signaling cytokines, including type I IFNs, TNF-α, IL-1α, IL-1β, and IL-33." (PMID 33680987, 2021). "Besides, TNF released by MCs in mice infected with E. coli increased the expression of E-selectin in local blood vessels, facilitating the recruitment of DC to the site of infection." (PMID 34211473, 2021). "Interestingly, RIPK3-deficient cells behaved like TNF-KO cells: upon MVA-infection, RIPK3-deficiency conferred no protection." (PMID 34711816, 2021).
infection (continued). "As Toll-like receptors (TLRs) are vital for innate immune cells to recognize pathogens, and tumor necrosis factor alpha (TNF-α) is an important pro-inflammatory cytokine, genetic variants of these genes could potentially strongly influence the host response during infection." (PMID 33961170, 2021). "Moreover, EBN restores the immune system in the context of infection by influencing viruses through regulation of pro-inflammatory cytokines, such as IL-6 and TNF-α, and cytokines with regulatory properties, such as IL-10 and CCL2, which are also involved in the progression of UC." (PMID 33967768, 2021). "However, an appropriate increase in TNF-α can also prevent infection." (PMID 34447797, 2021). "Chiang and coworkers demonstrated that NNV infection of the primary culture of brain cells from giant grouper (Epinephelus lanceolatus) activates microglial cell proliferation and secretion of proinflammatory cytokines (IL-1β and TNF-α) and subsequently the neural cell death." (PMID 34707620, 2021). "Upon infection, cardiac-resident cells, such as cardiomyocytes, endothelial cells, and fibroblasts, may contribute to acute inflammation by secreting cytokines such as IL-1β, IL-6, TNF-α, and IL-18." (PMID 34504807, 2021). "In addition, a fast and direct strategy to target the uncontrolled response of the immune system after the infection could be the use of molecules to inhibit the action of TNF and IFN-γ." (PMID 34201847, 2021). "Correlating with these data, higher TNF-α and IL-6 production was observed in vitro by LPS or Pam3CSK4-stimulation of equal numbers of total cells from the bone marrow and the spleen, or equal volumes of blood, from mice 7 or 14 days after the primary infection compared to uninfected mice." (PMID 34975887, 2021). "Interestingly, the inhibition of TNF-α and interleukin-6 prevented infection-induced cell death." (PMID 34829902, 2021). "Previous work on male genital schistosomiasis has shown that infection intensity, defined by seminal egg count, is strongly associated with elevated seminal cytokine concentrations including Th2 (IL-4), regulatory (IL-10), Th1 (IFN-γ) and pro-inflammatory (TNF-α) cytokines." (PMID 33737927, 2021). "Therefore, anti TNF-α therapy with careful attention to prevention of infection and protection of graft function, could be a therapeutic alternative during aggravation of symptoms in a refractory case." (PMID 33829404, 2021). "Except for IAVs, several studies have demonstrated the essential role of endogenous Gal-3 in infection-induced inflammatory response against either virus or bacteria invasion via inducing neutrophil infiltration or proinflammatory cytokine production such as IL-1β, TNF-α, and IFN-γ." (PMID 34065500, 2021). "However, as their use is becoming more common, there are reports of a higher incidence of maternal infections that might be related to the use of anti-TNFα treatment in pregnancy." (PMID 34122062, 2021). "Previous in silico analysis of cow mammary tissue based on an interaction network comprising common target genes shared between CoPS and H groups found TNFα gene expression may be regulated by four miRNA during CoPS infection, namely bta-miR-21-5p, bta-miR-146b, bta-miR-155 and bta-miR-223." (PMID 34663465, 2021). "The therapeutic effect of MPX was evaluated in a murine model, revealing that MPX could protect against lethal infection with E. coli in mice and reduce the expression of the inflammatory factors IL-2, IL-6, and TNF-α, thereby alleviating intestinal inflammation." (PMID 34177825, 2021). "On the other hand, F. nucleatum subsequential infection maintained the secretion levels of IL-1β, IL-6 and TNF-α in pulmonary epithelial cells compared to the single P. aeruginosa group, which may be due to the low cellular viability caused by P. aeruginosa pretreatment." (PMID 33816348, 2021).